ITGAX (integrin subunit alpha X)
Diseases named in the same sentence as ITGAX in open-access papers (continued):
Sharing a sentence is not in itself a finding about the gene and the disease.
periodontitis (7 papers, 2022 to 2025). An acute or chronic inflammatory process that affects the tissues that surround and support the teeth. "For further investigate the candidate regulatory mechanisms of key crosstalk genes (ITGAX and COL4A2) shared by intracranial aneurysms and periodontitis, we constructed a target gene-TF network." (PMID 38685029, 2024). "Therefore, we hypothesize that the immune process mediated by ITGAX and COL4A2 is central to the co-morbid mechanism of intracranial aneurysm and periodontitis." (PMID 38685029, 2024).
type 2 diabetes (7 papers, 2016 to 2025). "Some experiments have found that islet inflammation could promote beta cell dysfunction in type 2 diabetes with increased expression of ITGAX." (PMID 35281591, 2022). "ITGAX, also known as CD11C, is highly expressed in muscle of type 2 diabetes patients." (PMID 38331723, 2024).
colorectal tumor (5 papers, 2013 to 2024). "Expression of the four chemokines was positively correlated with the two DC markers [integrin alpha X (ITGAX) and CLEC9A] in human colorectal tumor samples." (PMID 36654820, 2022).
IgA nephropathy (5 papers, 2020 to 2024). "Although there are isolated reports of complement pathway risk alleles in IgA glomerulonephritis, the only major ones are ITGAM and ITGAX that code for integrins that facilitate complement-dependent phagocyte activation and immune complex clearance." (PMID 36316518, 2022).
dementia (4 papers, 2020 to 2023). Loss of intellectual abilities interfering with an individual's social and occupational functions. "These loci are associated with several dementia-related genes, including PON1, AP2A2, MAGI2, POT1, ITGAX, PACSIN1, SLC2A8, and EIF4E." (PMID 35299244, 2022). "The phenotypic transformation from homeostatic microglia towards reactive microglia in dementia pathologies is associated with TREM2, HLA-DRA, ENTPD1 (CD39), CD80 (B7-1), CD86 (B7-2), CCR5, CD274, ITGAX (CD11c), TIMD4 and MRC1." (PMID 33113879, 2020).
glaucoma (4 papers, 2017 to 2023). Increased pressure in the eyeball due to obstruction of the outflow of aqueous humor. "Finally, Cd11C (ITGAX), a membrane marker found at high levels in DCs among other cells, was overexpressed in patients treated for glaucoma." (PMID 38254630, 2023).
metastatic melanoma (4 papers, 2016 to 2025). A melanoma that has spread from its primary site to another anatomic site. "In metastatic melanoma, we observed ITGAX (alias CD11c), a marker expressed on myeloid cells with a well-known impact on classical and monocytic dendritic cell function, is more frequently mutated in non-T cell-inflamed tumors." (PMID 33106165, 2020). "In metastatic melanoma, DCTN1 was found to be associated with the presence of T cell-inflammation while ITGAX (alias CD11c) is more frequently mutated in non-T cell-inflamed tumors." (PMID 33106165, 2020).
Hepatic steatosis (3 papers, 2018 to 2023). Steatosis is a term used to denote lipid accumulation within hepatocytes. "Reduce the expression of macrophage marker adhesion G protein-coupled receptor E1 (ADGRE1) and M1 macrophage marker integrin α x (ITGAX), alleviate the inflammatory reaction and improve the liver steatosis." (PMID 37361209, 2023).
adenoma (2 papers, 2021 to 2022). A neoplasm arising from the epithelium. "Quantitative analysis of CD11c+ (also known as ITGAX+) stromal immature macrophage lineage cells (IMCs) and surfactant protein-C (SPC+; also known as SFTPC+) adenoma cells using flow cytometry confirmed that both cell types were robustly decreased by atorvastatin treatment." (PMID 34779486, 2022).
cognitive decline (2 papers, 2022 to 2024). "However, the expression of SPP1 and integrin subunit alpha X (ITGAX) is associated with cognitive decline and neuropathologies through the regulation of microglial subsets." (PMID 38919629, 2024).
diffuse midline glioma (2 papers, 2024 to 2025). A diffuse glioma that arises from the midline structures of the central nervous system. "This hypothesis-generating study characterized the mRNA expression profiles and prognostic impacts of antigen-presenting cell (APC) markers (CD14, CD163, CD86, and ITGAX/CD11c) in pediatric brainstem diffuse midline glioma (pbDMG) tumors." (PMID 38255296, 2024).
emphysema (2 papers, 2015 to 2024). "ITGAX was identified as one of the top seven genes, which is increased by >2.5-fold in emphysema patients." (PMID 38612871, 2024).
epilepsy (2 papers, 2021 to 2024). A brain disorder characterized by episodes of abnormally increased neuronal discharge resulting in transient episodes of sensory or motor neurological dysfunction, or psychic dysfunction. "In a KA-induced epilepsy model, we found that sitagliptin attenuated KA-induced epilepsy and increased the expression of ITGAX in microglia, which suggested that DPP4 inhibiting could promote DAM conversion." (PMID 33975617, 2021).
glomerular disease (2 papers, 2023 to 2025). "Compared with other glomerular disease controls, C3G showed glomerular upregulation of complement C3 with possible interactions with ITGAX (CD11c), a likewise upregulated integrin subunit which in turn had potential interactions with other highly enriched ECM-related proteins." (PMID 40416397, 2025).
Lipedema (2 papers, 2022). Disorder of adipose tissue characterized by symmetric and bilateral enlargement of the lower extremities due to abnormal deposition of subcutaneous fat often in obese women. "Through qPCR analysis, it has been found that CD11c (ITGAX)—a marker gene for immune-cell infiltration—had significantly higher expression in AT of lipedema tAT compared to the controls." (PMID 36551837, 2022). "On the molecular level, expression of the ITGAX gene (CD11c) significantly increased in lipedema thigh AT." (PMID 35625899, 2022).
thyroid cancer (2 papers, 2021). "At the cellular level, in the CCLE database, ALPL and ITGAX were expressed in various thyroid carcinoma cell lines." (PMID 34141614, 2021). "At the cellular level, ALPL and ITGAX were expressed in various thyroid cancer cell lines." (PMID 34141614, 2021).
acne (1 paper, 2022). An inflammatory process of the sebaceous glands which is characterized by comedones, nodules, papules and/or pustules on the skin. "Using a murine/human aGVHD gene signature we identified a cluster of ITGAX+CD14+S100A9+PTGS2+ macrophages that expanded in psoriatic but not acne skin compared with healthy controls." (PMID 35584681, 2022).
CAEBV infection (1 paper, 2006). "Eventually, we found several genes with expression levels significantly higher in cell lines established from NK/T-cell lymphoma than those from CAEBV infection: FGF14, PDCD4, PCNA, MAP2K4, ITGAX and AKAP2 were preferentially expressed in SNK/T cells established from nasal NK/T lymphoma." (PMID 16449999, 2006).
hepatopathy (1 paper, 2022). "Therefore, under certain circumstances, such as in vitro or hepatopathy, the expression of ITGAX by LSECs might be activated." (PMID 36211451, 2022).
immunotoxicity (1 paper, 2020). "Five genes (CD8A, CYP1A1, ITGAX, LYZ, and PTPRC) associated with immunotoxicity were among the most up‐regulated genes exposed to dose 1:8 indoor PM." (PMID 31883508, 2020).
intracranial hemorrhage (1 paper, 2025). Bleeding within the SKULL, including hemorrhages in the brain and the three membranes of MENINGES. "Therefore, LEF1, BLVRB, ITGAX and ATF4 are expected to become new biomarkers for intracranial hemorrhage." (PMID 40933575, 2025).
liver cancer (1 paper, 2022). An epithelial or non-epithelial malignant neoplasm that arises from the liver. "The expression of FCN2 was negatively correlated with the M1 macrophage biomarker (IRF5), neutrophil biomarker (ITGAM), and DC biomarker (ITGAX) in liver cancer." (PMID 36425563, 2022).
liver disease (1 paper, 2024). "To test if this mechanism is relevant in human disease, we analyzed integrin expression (ITGA4, ITGAX) in human blood monocytes from patients with liver disease obtained from KUMC Liver Bank." (PMID 38704651, 2024).
polycystic ovary syndrome (1 paper, 2022). A disorder that manifests as multiple cysts on the ovaries. "Two genes (GRIN2A and ITGAX) located on BTA25 were associated with CTFS in Iranian Holstein cattle and with altered expression in polycystic ovary syndrome in women, respectively." (PMID 35484513, 2022).
tumor (1,082 papers, 1996 to 2026). "ITGAX usually functions as a receptor for the extracellular matrix and is associated with tumor angiogenesis." (PMID 40308606, 2025). "Another paradoxical phenomenon is the upregulation of ITGAX which are associated with a possible influence on immune cell interactions within the tumor microenvironment, potentially affecting immune surveillance and tumor immunity." (PMID 40950184, 2025). "The most significant associations were for COL11A1 and ITGAX with tumor stage in GNCA, and UNG with metastasis, also in GNCA." (PMID 23717493, 2013). "Finally, the risk score was calculated by the following formula: tumor-associated endothelial signature score = 0.180855332*ADD1 + 0.059530341*ALOX12 + 0.145361104 *CXCL10 - 0.081730252*F2RL1 + 0.001225741*ITGAX − 0.004914148*MET." (PMID 37719845, 2023). "We found that the mRNA expression of C1QA, C1QB, C1QC, C5AR1, C3AR1, C1QR (CD93), CR1, CR2, CR3 (ITGAM), and CR4 (ITGAX) were positively associated with almost all kinds of tumor immune cells, including CD8+ T cells, CD4+ T cells, B cells, macrophages, monocytes and DCs." (PMID 34813686, 2022). "Divergent effects were observed for tumor Gleason score, with two genes being associated with a higher Gleason score (ITGAX; OR = 3.87 [1.88–7.56] and ZNF322; OR = 2.26 [1.27–4.02]) and two genes with a Gleason score <7 (CCL19; OR = 0.46 [0.24–0.88] and HIST1H1A; (OR = 0.45 [0.24–0.86])." (PMID 25411967, 2014). "First, we detected the mRNA expression of 21 risk genes and found that GDPD3, ITGAX, and FAM167B were significantly overexpressed in tumor tissues." (PMID 41562071, 2025). "Mice with upregulated ITGAX expression exhibited the fastest tumor growth, while the knockdown group showed the slowest growth." (PMID 39845786, 2024). "Involving other clinical parameters such as age at diagnosis, gender, and tumor content (%) in Cox survival analysis model 2, ITGAX,SAMSN1, TNFAIP2 and CD163 showed significant values." (PMID 39015503, 2024). "In this study, elevated ITGAX expression was correlated with greater tumor progression and increased vascular density, suggesting a role in enhancing the efficacy of antiangiogenic therapies." (PMID 39845786, 2024). "ITGAX had a lower promoter methylation level in, and thus displayed overexpression in, tumor vs. normal tissues in KIRP." (PMID 39436262, 2024). "Tumor necrosis promotes metastasis and is associated with poor prognosis; the presence of ITGAL, ITGAX, and TMEM119 in tumor necrosis suggests their roles in facilitating NSCLC progression." (PMID 37835514, 2023). "The stromal expressions of ITGAL and ITGAX, together with tumor expression of TMEM119 in NSCLC, were demonstrated." (PMID 37835514, 2023). "CD11c (ITGAX)-targeted protein vaccines for in vivo delivery of tumor antigens to DCs induce potent immune responses and antitumoral activities." (PMID 36797662, 2023). "Results show that C3AR1 has the strongest correlation with M2 macrophages (CD163, MRC1, CD209), tumor-associated macrophages (CCL2, CD86, CD68) and monocyte immune markers, including (CD14, CD33, ITGAX)." (PMID 37005667, 2023). "A correlation of immune cell marker genes, including tumor-associated macrophages (TAMs) (CD209, CD206/MRC1, IL6, IL8, and CXCL10), MDSCs (CD33 and IL6), dendritic cells (DCs) (CD11c/ITGAX, CD209, TNF, and CD80) and Fusobacterium has been found in humans." (PMID 33823861, 2021). "It is reported that ITGAX is involved in the angiogenesis of dendritic cells and tumor angiogenesis." (PMID 33976979, 2021). "We also assessed the correlations of CR4 expression (ITGAX, CD11c, αXβ2 integrin) with tumor immune infiltration levels in GC, and the results were roughly the same." (PMID 33614473, 2020). "They showed that high TGFB2 mRNA levels were associated with an immunologically “cold” tumor microenvironment (TME), characterized by low expression of antigen-presenting cell (APC) markers (e.g., CD14, CD163, ITGAX/CD11c), which impairs anti-tumor immune responses." (PMID 41373732, 2025).
tumor (continued). "In endothelial cells, ITGAX stimulates proliferation, migration and tumor angiogenesis." (PMID 36432612, 2022). "Especially, ENO2 had a correlation coefficient of more than 0.3, 0.4 and 0.5, respectively, with the 19, 16, and 5 out of 21 biomarkers, and had the highest correlation with ITGAX (R = 0.670) in dendritic cells, again supporting its potential vital role on tumor immune infiltration." (PMID 36362375, 2022). "Similarly, ITGAX was also detected in immune cells and tumor necrosis in LUAD and LUSC." (PMID 37835514, 2023). "To determine whether the greater MHC-II gene expression in CB tumors correlated with tumor or immune cells, we evaluated the dendritic cell genes ITGAX and FLT3 and the macrophage gene ITGAM, corresponding to the CD11b protein expressed on the surface of macrophages." (PMID 34548479, 2021). "We obtained results on the correlation between TPPP3 expression and marker genes of tumor infiltration-associated immune cells, including CD8+T cells (CD8A and CD8B), B cell (CD19 and CD79a), and Myeloid dendritic cell (HLA-DPB1, HLA-DQB1, HLA-DRA, HLA-DPA1, CD1C, NRP1, and ITGAX)." (PMID 33083464, 2020). "Conversely, the genes FTH1, SQSTM1, HSPA6, TSPYL2, PHLDA2, ITGAX, and DNAJA4 are expected to act as versatile protein regulators, potentially suppressing tumor cell genetic instability and promoting autophagy, apoptosis, and other forms of cell death." (PMID 40986633, 2025). "On the other hand, pRCC showed upregulation of TFPI2, FSTL1, FAS, and PIGR in the epithelial/tumor, C1QTNF3 and GRN in the endothelial, and ITGAX, HLA-DQA1, IL4I1, and CTSC in the immune compartments." (PMID 38703764, 2024). "PRDX6, MAGOHB, NUCKS1, DCAF13, and TXN displayed opposite trends on their potential facilitation of CTL function as well as correlations with immune checkpoints and TILs (tumor-infiltrating lymphocytes) compared to ITGAL, ITGAX, and TMEM119 in NSCLC." (PMID 37835514, 2023). "The promoter methylation levels of ITGAX, LAPTM5 and SERPINE1 in CCRCC tumor tissues were significantly lower than those in normal tissues." (PMID 33976979, 2021). "Firstly, the expression levels of ITGAX, LAPTM5, and SERPINE1 in CCRCC tumor tissues are significantly higher than those in normal tissues adjacent to cancer according to GEPIA database." (PMID 33976979, 2021). "For the validation of this analysis, the GEPIA expression level of the hub genes were also employed and gene- ITGAM, ITGAX, PTPRC along with STAT3 were found in lower expression levels in tumor cells." (PMID 33946372, 2021). "Further results showed that the ITGAX, LAPTM5, and SERPINE1 levels in CCRCC tumor tissues were significantly higher than those in normal tissues and were associated with poor prognosis." (PMID 33976979, 2021). "Importantly, we discovered that ICAM1 binding to the ITGAX/ITGB2 heterodimer facilitates neutrophil-monocyte crosstalk, skewing monocyte differentiation toward pro-tumor TAMs and fostering tumorigenesis." (PMID 40948800, 2025). "Although our study did not examine the interaction of ITGAX with the tumor microenvironment, this remains an important direction for future research." (PMID 39845786, 2024). "By taking advantage of the protein expression data within the Human Protein Atlas, we observed a general presence of ITGAL and ITGAX in the stromal compartment but not in tumor cells in both LUAD and LUSC." (PMID 37835514, 2023). "We observed that MFAP5 + fibroblasts were the main senders that could release complement C3 to interact with the receptors ITGAM/ITGB2, ITGAX/ITGB2, and C3AR1 of C1QC + macrophages in tumor tissues, thus activating the complement system." (PMID 37344903, 2023). "In contrast, ITGAX was expressed within inflammatory cell aggregates, but did not stain tumor and stromal cells." (PMID 33718208, 2021).
tumor (continued). "The decrease of promoter methylation of ITGAX, LAPTM5 and SERPINE1 in CCRCC tumor tissues indicates that the high expression of key genes in CCRCC might be relevant to the low methylation level." (PMID 33976979, 2021). "In addition, gene expression in the primary tumor (T-TIS) was higher compared to control (N-TIS) for most genes (TGFβ1, COL1A1, COL3A1, ITGAV, ITGAX) (matched samples)." (PMID 33718208, 2021). "Compared to naïve HL-60 human promyelocytic leukemia cells, which cannot be engulfed by tumor cells, differentiated HL-60 (dHL-60) neutrophils, which can be engulfed by tumor cells, express several integrin family genes, such as ICAM-1, ITGAM, ITGB2, ITGAX, and ITGAV, at higher levels." (PMID 39941753, 2025). "According to the Pearson’s correlation analysis, the tumor DLK2 level was negatively correlated with the expressions of M1 macrophage markers such as HLA class II histocompatibility antigen, DR α chain (HLA-DRA) (* p = 0.0278), CD11c (integrin α X, ITGAX) (p = 0.0557), and CD86 (p = 0.0783)." (PMID 35456435, 2022). "Analysis of bulk tumour mRNA displayed a strong correlation between ACTA2, a marker of MSCs, and matrix remodelling enzymes (MMP2), ECM proteins (VCAN, FN1, COL1A1), immunomodulatory molecules (Serpine1, CXCL12), innate immune cell markers (CD14, ITGAX) and adaptive immune cell markers (CD4)." (PMID 34885111, 2021). "On the other hand, Itgal, Itgax, and Tmem119 in LL2 tumors were downregulated by taxifolin; their human counterparts (ITGAL, ITGAX, and TMEM119) displayed positive T cell dysfunction values, suggesting their negative impact on CTL-derived cytotoxicity in tumor cells." (PMID 37835514, 2023).
infection (538 papers, 2005 to 2026). The state of being infected such as from the introduction of a foreign agent such as serum, vaccine, antigenic substance or organism. "The three most highly upregulated genes in the conjunctiva in response to infection were integrin subunit alpha X (ITGAX), myeloid cell nuclear differentiation antigen (MNDA) and pleckstrin (PLEK) triggering." (PMID 38694515, 2024). "Between month 6 and month 12 post-infection, persistent Bm cell clones upregulated genes associated with CD21–CD27–FcRL5+ Bm cells, including TBX21, ITGAX and FCRL5." (PMID 37106039, 2023). "Aligning with our RNA-seq data, ITGAX surface expression was not increased in infected PMNs compared to uninfected PMNs, although surface detection of CD11c was significantly decreased at 1h post-infection, suggesting it may be internalized during infection with Gc, possibly during phagocytosis." (PMID 38976720, 2024).